IL22 (interleukin 22)
Diseases named in the same sentence as IL22 in open-access papers (continued):
Sharing a sentence is not in itself a finding about the gene and the disease.
infection (continued). "In that case, IL-22 was mainly produced by γδ T cells and to a lesser extent by ILCs and NK cells during the early phase post-infection, and then by αβ T cells later after infection." (PMID 27752258, 2016). "Taken together, although IL-22 is expressed during T. cruzi infection, it plays a minor role in protection and pathology during the acute phase of experimental infection with the Tulahuen strain." (PMID 27650379, 2016). "In acute inflammation, IL-22 recruits inflammatory cells to clear the infection, probably through the local upregulation of chemokines in the lung, and to rescue lung epithelial cells from cell death." (PMID 27388918, 2016). "During a P. chabaudi infection CD4+ and CD8+ T cells were shown to produce IL-2231, whereas in a PbA infection γδ+ T cells beside others showed the highest ability to produce IL-22." (PMID 27311945, 2016). "The production of IFN-γ, IL-17A and IL-22 by colonic LP cells was reduced in Ccr2−/− mice on day 12 post infection." (PMID 26269452, 2015). "Recently, IL-22 has been found to play a major role in infections with the EHEC/EPEC like pathogen C. rodentium in mice." (PMID 25799189, 2015). "We found that Il22-/- mice exhibited increased tissue pathology compared with infections in wild-type mice." (PMID 26285207, 2015). "To determine the mechanism through which CD4+ T cells drive IEC proliferation during infection, we next examined levels of IL-22; a cytokine produced by CD4+ T cells during enteric infection that interacts with its receptors expressed by IEC." (PMID 26285214, 2015). "In order to determine if IL-22 contributes to resolution of a leishmanial infection, we infected Il22-/- mice with Leishmania major and L. braziliensis and monitored the course of infection." (PMID 26285207, 2015). "As early 3 days after infection there was an antigen specific production of IL-22, which was maintained at 2 and 5 weeks post-infection." (PMID 26285207, 2015). "IL-22 knock-out mice infected with C. rodentium that were administered IL-22 several days after infection had a high mortality rate compared to infected mice administered IL-22 at the beginning of infection." (PMID 26793707, 2015). "Consistently, LP cells from Rag1−/−CCR2WT mice produced robust amounts of IL-22 after C. rodentium infection, suggesting that ILCs are the major source of mucosal IL-22 in response to pathogen infection." (PMID 26269452, 2015). "This is in accordance with the observation that IL-22 is elevated in the colon in response to infection by C. difficile or C. rodentium." (PMID 26793707, 2015). "We found that Il-22 gene transcription, as well as IL-22 protein levels were dramatically reduced in the colons of Tcr-β-/- mice indicating that CD4+ T cells are the primary source of IL-22 at this time point in the infection." (PMID 26285214, 2015). "Deletion of IL-1β in blood monocytes blunts the production of IL-22 by ILC3 and increases the susceptibility to infection." (PMID 26269452, 2015). "Similar to infection, we observed a robust expression of the Th17-related genes RORγt, IL-23p19, IL-17F, IL-21 and IL-22." (PMID 26490738, 2015). "As expected, Ifng levels were increased following infection, and there was a similar increase in wild-type and Il22-/- mice." (PMID 26285207, 2015). "We examined the presence of CD4+ and CD8+ T cells, CD11b+ myeloid cells, and neutrophils in the lesions of L. major infected wild-type and Il22-/- mice at the peak of infection." (PMID 26285207, 2015). "The mucosal NKp44+ NK cell count was higher in the early acute infection phase than in the chronic infection phase (P < 0.05), and the IL-22 secretion from mucosal NKp44+ NK cells was higher in the early acute phase than in the chronic phase (P < 0.05)." (PMID 25759828, 2014). "IL-22 neutralization markedly increased infectious virus load in the liver as early as 2 days after infection." (PMID 24721575, 2014).
infection (continued). "In contrast, mycobacterial infection induced an early significant IL-22 secretion from primary epithelial cells that ended 24 hours after infection." (PMID 24489729, 2014). "IL-22 appears to play a dichotomous role in host defence depending on the nature of the pathogen and site of infection." (PMID 24586147, 2014). "Although T cells also importantly contribute to produce IL-22 after infection, early production of IL-22 is crucial for C. rodentium resistance, as Il22-/- mice rapidly succumb within the first 8–12 days after infection." (PMID 24744763, 2014). "Protective functions of IL-22 have been described in the context of extracellular pathogen infection of the lung and intestine including K. pneumoniae and C. rodentium." (PMID 24586147, 2014). "Mixed TcI/TcII infection in patients produces more IL-22 compared with infection with only one strain." (PMID 25371910, 2014). "Protective immunity in this infection requires IL-22 and IL-17, produced by different cells in two distinct phases." (PMID 25236797, 2014). "It is now important to dissect how and why certain infections elicit IL-22 responses that are favoured over IL-17-mediated immunity in humans." (PMID 24586147, 2014). "To directly prove the role of IL-22, we evaluated levels of IL-22, as well as of companion cytokines, such as IL-17A and IL-17F, in infection and the consequences of IL-22 inhibition or administration." (PMID 23853597, 2013). "Early after infection of C57BL/6 mice with Mtb real time RT-PCR of lung homogenates was conducted to compare gene expression of Il22 with the expression of Il17a, Il17f, Il12b, and Il23p19." (PMID 23460846, 2013). "Whereas IL-17A supports protective immune responses during mycobacterial infections, the role of IL-22 after infection with Mycobacterium tuberculosis (Mtb) is yet poorly characterized." (PMID 23460846, 2013). "Consistent with an effect of IL-21 on Th17 cells, plasma levels of IL-22 were higher in IL-21-treated than control animals at wk6 post infection (fold change wk6 vs. wk2: 5.6±1.82 vs. 1.02±0.39; P = 0.056)." (PMID 23853592, 2013). "siRNA-mediated silencing of IL-17 had no affect on the R. pusillus-related skin damage in the murine model system, further supporting the theory that IL-22 represents a key cytokine related to infection with this particular Rhizomucor species." (PMID 23798999, 2013). "We found here that NKp46+ cells expanded in the vagina in infection and produced IL-22, more than IL-17A, likely via AhR." (PMID 23853597, 2013). "In contrast, IL-22 has protective functions in models of microbe/infection-driven inflammation at host/environment interfaces, likely by up-regulating anti-microbial peptides, inducible nitric oxide (NO) synthase and mucus production." (PMID 22967278, 2012). "those that are highly upregulated by infection of both the virulent and avirulent strains (IL-22, IL-17A, IL-17F and iNOS); and iv." (PMID 22675469, 2012). "After 8 hours of infection, at the more acute phase, the virulent strain had induced an extensive increase in many cytokines, particularly IL-22, IL-17A and IL-17F (132 to 233 fold)." (PMID 22675469, 2012). "Beyond the known inflammatory mediators, we identified IL-22, IL-17A and IL-17F as highly upregulated cytokines and as first responders to infection during the innate phase of the host immune response." (PMID 22675469, 2012). "A possible explanation is that Il22−/− showed a decrease in Cxcr2 expression after the peripheral infection had established (day 4 p.i.), and Il22−/− were also defective in brain Cxcl1 and Cxcl5 expression." (PMID 22952908, 2012). "Of particular interest is the association among serum IL-22, CRP and spontaneous bacterial peritonitis, indicating that IL-22 production is augmented by the infection." (PMID 22967278, 2012).
infection (continued). "Infection also induced significant but low level increases in NTHi-induced IL-5, IL-13, IL-17 and IL-22, and higher levels of IFN-γ release from mediastinal lymph nodes (MLN) cultures after 5 days, which returned to baseline levels after 26 days." (PMID 21998577, 2011). "IL-22, a member of the IL-10 family, is important in epithelial cell homeostasis, in infection and inflammation." (PMID 21977228, 2011). "In contrast, IL-22 plays only a marginal role for infection control during primary influenza virus infection in the lung." (PMID 21789181, 2011). "Immunoneutralization of IL-22 prior to high-dose infection in HeJ-NIH mice also resulted in earlier mean mortality (11 days) than in mice receiving isotype control (14.5 days)." (PMID 22046427, 2011). "Following bleomycin increased numbers of IL-22 producing Th17 cells have been reported whereas following infection with Bacillus subtilis γδ T cells seem to be the major source of IL-22 production." (PMID 21789181, 2011). "A similar pattern of IL-22 secretion was observed at days 5 and 7 post infection (p.i.)in serum and splenocyte supernatants, as well as in the liver (data not shown)." (PMID 21347242, 2011). "The current study investigates the production of IL-22, and the role that IL-22 plays during primary and secondary LM infection, using both systemic and mucosal routes of infection." (PMID 21347242, 2011). "In fact, the reduced expression of S100A8, which is one of the antimicrobial proteins against C. rodentium and is regulated by IL-22, was also detected in VillinCre-p38ΔIEC epithelial cells after infection." (PMID 20532209, 2010). "Both innate and adaptive T cell-immunity to C. jejuni infection led to the release of IFNγ, IL-22 and IL-17A; suggesting a critical role for this cytokine triad in establishing host anti-microbial immunity during the acute and effectors phase of infection." (PMID 21085698, 2010). "Surprisingly, although numbers of IL-17-producing T cells increased significantly over time after the infection, the magnitude of increase in IL-17-producing T cells was significantly lower than that in IL-22-producing T cells at weeks 6–8 after the infection." (PMID 20195465, 2010). "It would be interesting to investigate if this IL-23-mediated IL-17/IL-22 immunity occurs in human infections." (PMID 21085698, 2010). "Specifically, IL-22 ameliorated disease in selected models of microbe/infection-driven inflammation at host/environment interfaces." (PMID 20976193, 2010). "cholerae infection and prophylactic treatment with an IL22 Fc-fusion protein." (PMID 41959413, 2026). "Consistent with very low levels of infection, transcripts of immune mediators Il22 and Ifnl2/3, previously shown to be upregulated following robust RV infection, were not significantly increased in the infected Atoh1cKO intestine as compared to uninfected cKO littermates." (PMID 39727412, 2025). "Moreover, the onset of skeletal muscle necrosis in the IL-22 intervention group (on the sixth day after infection, or the fifth day after intervention) was delayed compared to the untreated group (on the third day after infection)." (PMID 40006939, 2025). "However, S. typhimurium exploits this pathway by inducing IL-23 through TLR5-Myd88 signaling in DCs, leading to elevated IL-22 production from ILC3s, which in turn facilitates infection." (PMID 40872304, 2025). "Cytokine levels decreased for 6 of 9 assayed cytokines or the chemokine in the Chr7×3 AAB variant (IL-17a, IL-22, IL-5, IFN-γ, TNF-α, and IL-1β) and further decreased for all cytokines and the CXCL1 chemokine in the Chr7×3 ABB variant when compared to infection with Chr7×2 SC5314." (PMID 39896449, 2025). "IL-22 supplementation intensified the fibrosis whereas rIL-22BP intervention significantly attenuated collagen deposition with the most pronounced protection observed at 3 months post-infection." (PMID 41562076, 2025).
infection (continued). "The expression levels of IL-17 and IL-22 may be important factors affecting the survival rate of mice after infection." (PMID 40006939, 2025). "These effector T cells return to the infection site and serve as an adaptive source of IL-22." (PMID 40872304, 2025). "The diminished expression of IL‐22 has also been documented in TPN utilization; however, whether alterations in ILC3s are associated with TPN‐related infections remains unclear." (PMID 40236767, 2025). "These previously published findings and our current study highlight how dietary fats govern critical innate immune responses, notably IL-23 and IL-22 responses, to intestinal injury or pathogen infection and dictate the hosťs ability to resolve intestinal injury." (PMID 40502773, 2025). "While FT did not prevent weight loss during the early phase of infection, FT-treated Il22−/− mice began to recover from 9 dpi, ultimately regaining body weight comparable to that of Il22+/+ mice by 20 dpi." (PMID 41361166, 2025). "Importantly, injection of anti-IL-13, at 2- and 4-days post CR infection, diminished local secretion of IL-10 and IL-22." (PMID 40591723, 2025). "Although IL-22 is important for maintaining epithelial integrity and limiting infection-induced damage, IL-22-independent pathways can compensate in its absence, enabling bacterial clearance and regeneration of the colonic epithelium when hydration is restored." (PMID 41361166, 2025). "Cytokine levels decreased for 6 of 9 assayed cytokines or the chemokine in the Chr7x3 AAB variant (IL-17a, IL-22, IL-5, IFN-γ, TNF-α, and IL-1β) and further decreased for all cytokines and the CXCL1 chemokine in the Chr7x3 ABB variant when compared to infection with Chr7x2 SC5314." (PMID 40577316, 2025). "For example, the absence of IL-22 does not increase host susceptibility during infection with Neisseria gonorrhoeae, Listeria monocytogenes, or Salmonella enterica serovar Typhimurium (21, –, 24)." (PMID 38557196, 2024). "A recent study suggests that IL-22 can also act on lung epithelial cells and promote dysplastic cell formation, indicating that infection-induced inflammatory factors may work in a cooperative manner to control lung dysplastic remodeling." (PMID 39352385, 2024). "Thus, it has been shown that, in keratinocytes IL-22 induces the production of antimicrobial peptides such as human beta defensin-2 (HBD-2) which plays a key role in host defense against infection." (PMID 38431633, 2024). "Therefore, the integrity of the airway-blood barrier in the context of R265-induced eosinophilic allergy also relies on the IL-22 production as well as the promotion of Th2 profile, characteristic of R265 infection." (PMID 39635124, 2024). "Therefore, here we describe important implications concerning the roles of IL-22 cytokine during R265 experimental infection." (PMID 39635124, 2024). "IL-22 is pivotal in generating innate immune responses against various infections." (PMID 39195286, 2024). "As expected, infection with C. rodentium induced the expression of IL-22 in ILC3s." (PMID 39253083, 2024). "Taken together, these results indicate that caspase-1 and −11 are involved in the infection-induced upregulation of IL-22 in the gut, consequently inducing the expression of antimicrobial C-type lectins as well as Fut2, which encodes for an enzyme important for fucosylation in the gut." (PMID 39428744, 2024). "Because Il22−/− mice displayed lower induction of some antimicrobial genes in the gut, we investigated whether specific IL-22-dependent antimicrobial responses contributed to host protection during this infection." (PMID 38557196, 2024). "This might be attributed to the peak expression of IL-22 occurring on the third day after infection, while differences in regenerative response occurred in the early stages following infection." (PMID 38905308, 2024).
infection (continued). "Moreover, infection with S. aureus reportedly elevates IL-22–derived γδ T cells in mechanically injured skin, and these cells have been identified as protective against S. aureus reinfection by producing TNF-α and IFN-γ via the TLR2/MyD88 signaling pathway." (PMID 38319737, 2024). "In contrast, the b2 mucus layer thickness was comparable for WT and Il22−/− mice after infection." (PMID 39428744, 2024). "During infection, IL-22 confers protection to the host by stimulating epithelial cells to produce antimicrobial proteins, including the C-type lectins Reg3β and Reg3γ, which exhibit direct antimicrobial activity against a subset of bacterial pathogens (7, 9, –, 13)." (PMID 38557196, 2024). "We next tested the impact of IL-22 on mucin release during infection." (PMID 39428744, 2024). "Additionally, our research broadens our understanding of the role IL-22 plays in maintaining and repairing the integrity of the gut epithelial barrier in the recovery phase of infection." (PMID 38557196, 2024). "Notably, FcεR1γ-deficient ILC3s showed a significant decrease in the expression of infection-induced immune activation genes, such as Fcgr3, Ccr7, Il22, Il17a and Cd93." (PMID 39013884, 2024). "Accordingly, IL-22 regulates neutrophilic infiltration in the lungs, thereby, restricting the effectiveness of neutrophilic proteases on the lung microenvironment, limiting the lung damage in case of intracellular infection." (PMID 39635124, 2024). "ILCs of the ILC22 type include NKp46(+) and lymphoid tissue-inducer (LTi)-like subsets that express AHR and protect the intestinal mucosa from infection by secreting IL-22 that acts on mucosal epithelial cells, inducing their survival, proliferation, and secretion of antimicrobial peptides." (PMID 38674118, 2024). "Similarly, while IL-18 supplementation did not affect the mucus barrier layer in the distal colon under baseline conditions, it did induce a significant increase in the mucus layer thickness of the Il22−/− mice during infection." (PMID 39428744, 2024). "To examine whether the lethal infection of CR occurs restrictedly in Il22-/- mice, we carried out oral CR infection in GF Rag1-/- mice, another immunocompromised strain where the V(D)J recombination activation gene Rag1 was deleted." (PMID 39630719, 2024). "Notably, CD4+ T cells from C. rodetium-infected VillinCre MHCIIflox/flox mice exhibited reduced production of IL-22 and IL-17A during the late phase of infection." (PMID 39379604, 2024). "The expression levels of Lcn2, which encodes for the antimicrobial protein lipocalin-2, and of S100a8 and S100a9, whose gene products together form the antimicrobial protein calprotectin, were increased during infection but were comparable between WT mice and Il22−/− mice." (PMID 38557196, 2024). "While the role of IL-22 in protection against respiratory pathogens such as M. haemolytica and M. ovipneumoniae is not clear, IL-22 has been shown to modulate immune responses during infection at mucosal surfaces." (PMID 36656850, 2023). "This illustrates the dynamic nature of inflammatory responses during C. rodentium infection, as additional IL-22 analyses in Casp8–/–Ripk3–/– mice at 7 dpi revealed that these mice produced less IL-22 than their Casp8+/-Ripk3–/– littermates at this stage of the infection." (PMID 37080966, 2023). "While suppression of IL-22–driven epithelial MHC II may be beneficial in chronic inflammatory conditions, it may increase susceptibility to infection by delaying initiation of appropriate immune responses." (PMID 37695525, 2023). "To assess if reduced BC hyperplasia observed in IL-22 LOF mice was associated with reduced epithelial proliferation, we measured the BC proliferative index by immunofluorescence of Ki67 and Krt5 following PR8 infection." (PMID 37726288, 2023). "Moreover, upregulation of RORγt, IL-21 and IL-22 indicates a pronounced Th17 immune response following infection in vaccinated mice." (PMID 36918600, 2023).